GHSR (growth hormone secretagogue receptor)
Description:
G protein-coupled receptor specific to ghrelin, an appetite-regulating peptide hormone commonly found in stomach. Upon activation, stimulates appetite and promotes growth hormone secretion. Also binds other growth hormone releasing peptides (GHRP) (e.g. Met-enkephalin and GHRP-6) as well as non-peptide, low molecular weight secretagogues (e.g. L-692, 429, MK-0677, adenosine).
Synonyms: GHS-R; GHS-R1a; GHSR-1a; GHDP
Tractability: Small molecule: an approved drug acts on it; a structure with a bound ligand is known; a high-quality ligand is known; it belongs to a druggable protein family. Antibody: its Gene Ontology location is reachable by antibodies, with high confidence; UniProt places it where antibodies can reach, with medium confidence; UniProt predicts a signal peptide or a membrane-spanning region. PROTAC: a small molecule that binds it is known. Other modalities: a drug acting on it is in phase 2 or 3 trials.
Target class: GRP-related receptor; Short peptide receptor (family A GPCR); Membrane receptor; Family A G protein-coupled receptor; Peptide receptor (family A GPCR)
Chemical probes: CHEMBL3586032, YIL781
Safety:
Unwanted effects reported when the protein is acted on. In parentheses: how it was acted on, where the effect was seen, and who reports it.
adrenocorticotropic hormone release (activation; cardiovascular system, endocrine; source: Urban et al. (2012))
appetite stimulation (activation; cardiovascular system, endocrine; source: Urban et al. (2012))
cardiovascular effects (reduced rates of left ventricular contraction and relaxation, hypertension, tachycardia) (inhibition; cardiovascular system, endocrine; source: Urban et al. (2012))
cortisol release (activation; cardiovascular system, endocrine; source: Urban et al. (2012))
energy homeostasis (activation; cardiovascular system, endocrine; source: Urban et al. (2012))
gastric motility (inhibition; cardiovascular system, endocrine; source: Urban et al. (2012))
growth hormone release (activation; cardiovascular system, endocrine; source: Urban et al. (2012))
hyperglycemia (activation; cardiovascular system, endocrine; source: Urban et al. (2012))
hypotension (activation; cardiovascular system, endocrine; source: Urban et al. (2012))
reduced insulin secretion (activation; cardiovascular system, endocrine; source: Urban et al. (2012))
Gene: Protein-coding gene on chromosome 3 (172,443,291 to 172,448,456, reverse strand). Ensembl gene ENSG00000121853.
Subcellular location: Cell membrane
Pathways (Reactome):
Signal Transduction: G alpha (q) signalling events; Peptide ligand-binding receptors
Gene Ontology:
Molecular function: G protein-coupled receptor activity; growth hormone secretagogue receptor activity; growth hormone-releasing hormone receptor activity; coreceptor activity; peptide hormone binding
Biological process: actin polymerization or depolymerization; decidualization; G protein-coupled receptor signaling pathway; hormone-mediated signaling pathway; negative regulation of inflammatory response; negative regulation of interleukin-1 beta production; negative regulation of interleukin-6 production; negative regulation of tumor necrosis factor production; positive regulation of multicellular organism growth; response to hormone; adult feeding behavior; growth hormone secretion; learning; memory; phospholipase C-activating G protein-coupled receptor signaling pathway; positive regulation of appetite; regulation of defecation; regulation of synaptic plasticity; cellular response to hormone stimulus; cellular response to insulin-like growth factor stimulus; cellular response to lipopolysaccharide; cellular response to thyroid hormone stimulus; female pregnancy; ghrelin secretion; learning or memory; and 26 more
Cellular component: cell surface; membrane raft; neuron projection; plasma membrane; glutamatergic synapse; membrane; postsynapse; Schaffer collateral - CA1 synapse; synaptic membrane
Genetic constraint (gnomAD): Loss-of-function variants: 17 observed, 24.69 expected, observed/expected ratio (o/e) 0.69, 90% interval 0.47 to 1.03. The upper end of that interval is the gene's LOEUF score, 1.03, which puts it in group 4 of 6, group 1 being the genes least tolerant of losing a copy. Missense variants: 504 observed, 508.61 expected, observed/expected ratio (o/e) 0.99, 90% interval 0.92 to 1.07. Synonymous variants: 238 observed, 223.74 expected, observed/expected ratio (o/e) 1.06, 90% interval 0.96 to 1.18.
Homologues: Orthologues: chimpanzee GHSR (100% identical), macaque GHSR (99% identical), rat Ghsr (96% identical), mouse Ghsr (95% identical), rabbit GHSR (95% identical), pig GHSR (93% identical), dog GHSR (86% identical), guinea pig GHSR (74% identical), tropical clawed frog ghsr (72% identical), zebrafish ghsra (67% identical), zebrafish ghsrb (66% identical). Paralogues in human: MLNR (50% identical), NTSR1 (31% identical), NMUR1 (30% identical), NMUR2 (27% identical), NTSR2 (25% identical), TRHR (25% identical), GPR39 (24% identical), EDNRA (22% identical), BRS3 (21% identical), EDNRB (21% identical), GRPR (20% identical), NMBR (20% identical), and 3 more.
Diseases named in the same sentence as GHSR in open-access papers:
GHSR is named in the same sentence as 177 diseases in open-access papers, as found by Europe PMC text mining. Sharing a sentence is not in itself a finding about the gene and the disease. The quoted sentences say what the papers report.
Obesity (104 papers, 2008 to 2026). Accumulation of substantial excess body fat. "Functional effects of five obesity-associated MRAP2 variants were analysed in HEK293 cells by co-expressing wild-type or variant MRAP2 with MC4R or GHSR." (PMID 41758604, 2026). "Our findings suggest a link between GHSR-1a and macrophage/monocyte infiltration, macrophage polarization, and adipocytokine secretion in atherosclerotic plaques associated with obesity-induced PVAT dysfunction." (PMID 40137085, 2025). "Several loss-of-function mutations of GHSR-1a, such as Ala204Glu and Phe279Leu, lead to obesity in humans, caused by a compensatory response in the form of upregulated expression of GHSR-1a." (PMID 40137085, 2025). "Obesity is associated with low-grade chronic inflammation; previously, we reported that global ablation of GHSR mitigates high fructose corn syrup-induced adipose and hepatic inflammation." (PMID 38464534, 2024). "In the current study, we investigated the effects of β-cell GHSR deficiency on glycemic regulation in obesity and aging using Ghsr-βKO mice." (PMID 38794702, 2024). "This is potentially mediated by a LEAP2-associated increase in obesity that serves to competitively bind GHSR and inhibit biological signalling." (PMID 34815532, 2022). "We previously reported that ablation of the ghrelin receptor, growth hormone secretagogue receptor (GHS-R), attenuates age-associated obesity and insulin resistance." (PMID 25543537, 2014). "Given the association between novelty seeking and food reward, our observation is partly in line with previous studies suggesting an association of ghrelin or GHSR SNPs with obesity or overeating." (PMID 23227170, 2012). "Previous studies have implied not only an effect of common GHSR variants on the pathogenesis of obesity but also of rare variants." (PMID 20404923, 2010). "Obesity case-control study of the −151 C/T GHSR promoter variant in Danes from the Inter99 study, the Danish ADDITION Screening Study and the Steno Diabetes Center." (PMID 20404923, 2010). "GHSR haplotypes have previously been associated with obesity, yet the only overlapping variant in these haplotype studies was rs572169." (PMID 20404923, 2010). "Common variants in GHSR were also associated with obesity and obesity-related traits in a French case-control study of 602 subjects; yet replication of such an association in a German study sample of 888 individuals failed." (PMID 20404923, 2010). "To clarify if common variations in GHSR associate with obesity in a Danish study population we genotyped seven SNPs in GHSR including a region of 11 kbp (HapMap build 35; region: 173640000–173651000 bp)." (PMID 20404923, 2010). "In humans, the GHSR gene lies within a quantitative trait locus strongly linked to multiple phenotypes related to obesity and the metabolic syndrome." (PMID 18698404, 2008). "In summary, results of our study suggest that polymorphisms in the GHSR gene are longitudinally associated with obesity and glucose metabolism in a prospective study setting." (PMID 18698404, 2008). "As obesity is associated with cognitive dysfunction, including memory, and learning impairments, we assessed whether neuronal loss of GHSR affects DIO-induced impairment in learning and memory." (PMID 38464534, 2024). "These GPCRs include melanocortin receptor-4 (MC4R), a central regulator of appetite, inactivating mutations of which are the most common genetic cause of obesity, and the receptor for ghrelin (growth hormone secretagogue receptor, GHSR), which enhances appetite." (PMID 39574659, 2024). "Inhibition of GHSR could suppress lipid uptake in endothelial cells, potentially reducing fat accumulation and improving metabolic disorders associated with obesity." (PMID 39796581, 2024). "Interestingly, carriers of some of these GHSR mutations demonstrate an incomplete penetrance of overweight and obesity, although the relationship of the mutation and the body weight phenotypes have not been confirmed." (PMID 23882175, 2013).
Obesity (continued). "Thus, we investigated SNPs in the GHSR gene and their association with obesity, glucose and insulin metabolism, and the conversion from impaired glucose tolerance (IGT) to type 2 diabetes in participants of the Finnish Diabetes Prevention Study (DPS)." (PMID 18698404, 2008). "GHSR-deficient mice show resistance to diet-induced obesity when supplied with a high-fat diet early in life, which implicates that functional ghrelin signalling is required for the full development of diet-induced obesity." (PMID 18698404, 2008). "Also, analyses of GHSR haplotypes lack consistent associations with obesity related traits." (PMID 20404923, 2010). "In obesity, recent research revealed that increased expression of the growth hormone secretagogue receptor (GHSR) in macrophages plays a pivotal role in the development of meta-inflammation, promoting macrophage infiltration and pro-inflammatory polarization." (PMID 40137085, 2025). "This study aimed to examine the association between GHSR-1a expression in atherosclerotic plaques and adjacent perivascular adipose tissue (PVAT) from 11 patients with obesity and peripheral artery disease (PAD) who underwent revascularization procedures." (PMID 40137085, 2025). "Due to the orexigenic properties of ghrelin, GHSR antagonists have been proposed for the treatment of obesity and diabetes." (PMID 40479577, 2025). "As a nutrient sensor, ghrelin increases appetite and promotes obesity by signaling through its receptor GHSR." (PMID 38464534, 2024). "Here, we investigate the effects of a long-term (12-month) high-fat (HFD) versus regular diet on obesity-related measures in global GHSR-KO and wild-type (WT) Wistar male and female rats." (PMID 38796563, 2024). "Collectively, our in vivo and in vitro results unequivocally demonstrated that inhibition of GHSR mitigates neuroinflammation under obesity, likely by reprogramming the AMPK-autophagy axis in neurons." (PMID 38464534, 2024). "This potential role of PF-5190457 should be further investigated in eating behaviors and obesity, an approach that is also in line with our recent pharmacological and transgenic rat work on GHSR and obesity." (PMID 39704175, 2024). "In the current study, we further investigated the effects of GHSR on insulin secretion in male mice under diet-induced obesity (DIO) and streptozotocin (STZ)-induced β-cell injury in aging." (PMID 38794702, 2024). "Deletion of the ghrelin receptor (GHSR) gene protects against diet-induced obesity and decreases food intake during a high-fat diet in male but not female rats." (PMID 38796563, 2024). "Ghrelin is a circulating brain–gut peptide hormone that promotes growth hormone secretion via binding to the growth hormone secretagogue receptor (GHSR) and participates in the regulation of insulin resistance, obesity, and inflammation." (PMID 38532900, 2024). "Here we investigated the effects of a long-term (12 month) high-fat (HFD) versus regular diet on obesity-related measures in global GHSR-KO and wild type (WT) Wistar male and female rats." (PMID 37886546, 2023). "This viewpoint is reinforced by a paper that showed improvements in obesity and diabetes when levels of acyl ghrelin were reduced, levels of Leap2 were increased, or GHSR activity was blocked." (PMID 36936164, 2023). "Ghrelin, another gastrointestinal cytokines, acts via the growth hormone secretagogue receptor (GHSR) and is known to increase appetite and promote obesity." (PMID 35273574, 2022). "Envisioned strategies to harness ghrelin biology for potential treatment of obesity include suppression of active circulating hormone and antagonism of signalling at its receptor, the growth hormone secretagogue receptor (GHSR)." (PMID 34815532, 2022). "The orexigenic hormone ghrelin increases food intake and promotes obesity through its receptor, growth hormone secretagogue receptor (GHS-R)." (PMID 35204795, 2022).
Obesity (continued). "Ghrelin and its receptor Growth Hormone Secretagogue Receptor (GHS-R), have been implicated in the pathogenesis of obesity and type 2 diabetes." (PMID 33793646, 2021). "Ghrelin is a GI hormone that specifically recognizes the endogenous ghrelin receptor, also known as growth hormone secretagogue receptor (GHSR), in the hypothalamus, which regulates food intake and obesity." (PMID 33968794, 2021). "The present study demonstrates for the first time that E2 replacement suppresses energy intake and obesity via the reduction of GHSR protein level in the stomach of HFD-fed OVX rats." (PMID 32224927, 2020). "The ablation of the ghrelin receptor, the growth hormone secretagogue receptor (GHS-R), decreases the risk of age-associated obesity and insulin resistance." (PMID 31281288, 2019). "More importantly, GHSR signaling is also an attractive target for the therapy of obesity-related metabolic disease; however a study showed that its ligand, ghrelin, was lower in obese subjects than in a normal group." (PMID 30405536, 2018). "GHSR, as a G protein-coupled receptor, was found to function in a highly ligand-independent way, highlighting the potential of GHSR inverse agonists in the field of obesity therapy." (PMID 30405536, 2018). "Knockout of GHSR improves the obesity and glucose metabolic disorders, suggesting a crucial role of ghrelin activity in insulin resistance." (PMID 30112394, 2018). "Zigman and colleagues, amongst others, have demonstrated that GHSR-1a-null mice are resistant to diet-induced obesity." (PMID 28134808, 2017). "Ghrelin stimulates the release of growth hormone (GH), food intake and obesity through its endogenous receptor, the growth hormone secretagogue receptor (GHS-R)." (PMID 28629187, 2017). "Pharmacological evaluation in obesity-induced rats revealed that a BBB penetrant inverse agonist for the GHSR-1a effectively reduced weight gain." (PMID 28134808, 2017). "Ghrelin is an endogenous ligand of the growth hormone secretagogue receptor (GHS-R) and has several biological activities, including the stimulation of GH secretion and promotion of food intake, which has been linked to obesity." (PMID 24465706, 2014). "They found that food intake and body weights of GHSR knockout ob/ob mice were similar to those of ob/ob mice, possibly suggesting that the obesity in ob/ob mice is unrelated to unopposed ghrelin action." (PMID 23882175, 2013). "For instance, GHSR-KO mice are protected from diet-induced obesity and glucose intolerance when chronically exposed to high fat diet." (PMID 23630616, 2013). "Haplotype analysis of the identified GHSR haplotypes among 15,854 Danes on quantitative traits related to obesity." (PMID 20404923, 2010). "When linkage analysis was performed in the Danish and Czech pedigrees they showed a LOD score for obesity at the GHSR locus of Z = 1.7." (PMID 20404923, 2010). "We investigate whether obesity-associated variants of MRAP2 alter their ability to modulate MC4R and GHSR signalling as a possible mechanistic link to the development of obesity." (PMID 41758604, 2026). "This pro-inflammatory effect of GHSR-1a may be due to the pro-inflammatory action of obesity-related dysfunctional PVAT observed in aging." (PMID 40137085, 2025). "Similarly, changes in ghrelin signaling and GHSR expression have been observed in obesity, leading to increased appetite and decreased energy expenditure." (PMID 40087612, 2025). "Collectively, our findings indicate that β-cell GHSR has a major impact on insulin secretion in aging but not obesity, and GHSR deficiency protects against STZ-induced β-cell injury in aging." (PMID 38794702, 2024). "Therefore, the deletion of GHSR gene provides a compelling proof-of-concept approach to investigate all the roles of this receptor in feeding behaviors and obesity." (PMID 38796563, 2024).